HTT (huntingtin)
Diseases named in the same sentence as HTT in open-access papers (continued):
Sharing a sentence is not in itself a finding about the gene and the disease.
Huntington disease (continued). "Huntington’s disease (HD) is an inherited disorder resulting from expansion of a trinucleotide (CAG, cytosine/adenine/guanine) repeat that encodes a polyglutamine tract in the huntingtin gene." (PMID 33207828, 2020). "In Huntington’s disease, mutant huntingtin protein is known to affect several stages in autophagy." (PMID 32998777, 2020). "Huntington’s disease (HD) is an inherited neurodegenerative disease with a middle age clinical onset that highly depends upon the length of the CAG repeated sequence (>35) present in the first exon of the huntingtin gene (OMIM 143100)." (PMID 31941072, 2020). "This is a particularly attractive target as it is upstream of the pathogenic HTT protein, and therefore, understanding how the HTT mRNA is processed in the context of Huntington’s disease could inform future therapeutic strategies." (PMID 32820193, 2020). "We propose that increased CSF NfL and mutant huntingtin concentrations might be the earliest detectable pathological events in Huntington's disease." (PMID 32470422, 2020). "In Huntington's disease, mutant huntingtin (HTT) protein sequesters FUS in neuronal inclusions." (PMID 32292882, 2020). "Huntington disease (HD), a devastating hereditary neurodegenerative disorder, is caused by an expansion of a CAG trinucleotide repeat that encodes a polyglutamine (polyQ) tract in the huntingtin (HTT) gene." (PMID 32978366, 2020). "With several potential disease-modifying treatments in development for Huntington's disease, including mutant and total huntingtin-lowering approaches, identifying the optimum time to treat and suitable biomarkers for trials in early preHD is of timely importance." (PMID 32470422, 2020). "Recent studies showed that such aberrant phase transitions are also involved in neurodegenerative diseases, affecting neuronal proteins such as Fused in Sarcoma (FUS) in Amyotrophic Lateral Sclerosis (ALS), Tau in Alzheimer's disease (AD) and huntingtin exon 1 in Huntington's disease (HD)." (PMID 33138914, 2020). "Huntington's disease (HD) is a hereditary and progressive nervous system disorder that is caused by a CAG trinucleotide repeat expansion in the first exon of the HTT gene, which encodes for the huntingtin protein (HTT)." (PMID 33299404, 2020). "Huntington’s disease (HD) is an autosomal-dominant neurodegenerative disorder caused by the abnormal expansion of cytosine-adenine-guanine (CAG) repeats in exon 1 of the huntingtin gene, which encodes a 350-kDa protein termed Huntingtin." (PMID 33071737, 2020). "Huntington’s disease (HD) is characterized by protein inclusions and loss of striatal neurons which result from expanded CAG repeats in the poly-glutamine (polyQ) region of the huntingtin (HTT) gene." (PMID 32611447, 2020). "Huntington’s disease (HD) is a genetic neurodegenerative pathology where a CGA triplet repeat expansion on the huntingtin gene (HTT) originates as an expanded polyglutamine segment in the huntingtin protein." (PMID 31963750, 2020). "Huntington’s disease (HD) is an autosomal dominant progressive neurodegenerative disease involving the loss of neurons in the cortex and striatum caused by amplification of the CAG trinucleotide repeat length in the Huntingtin (HTT) gene." (PMID 32581706, 2020). "Huntington disease (HD) is a devastating neurodegenerative disorder caused by the expansion of a CAG trinucleotide repeat within the first exon of the HTT gene, which encodes huntingtin." (PMID 32781742, 2020). "There is still no successful strategy to treat Huntington’s disease, an inherited autosomal disorder associated with the aggregation of mutated forms of the huntingtin protein containing polyglutamine tracts with more than 36 repeats." (PMID 31110208, 2019). "Our data show that Hsp90 is necessary to maintain the levels of REST and mHtt, which suggests that the interactions between Hsp90-REST and Hsp90-Huntingtin could be potential therapeutic targets to Huntington ́s disease." (PMID 31361762, 2019).
Huntington disease (continued). "•MitoPQ increases huntingtin aggregation in a cell model of Huntington's disease." (PMID 30389496, 2019). "Immunohistochemistry has revealed the presence of TDP-43 in the majority of the Huntington's disease patient cases, where it was found to be co-localized with the huntingtin protein in the dystrophic neurites and the intracellular inclusions but was absent from the intra-nuclear regions." (PMID 30837838, 2019). "However, when the healthy huntingtin was replaced with the mutant version found in Huntington’s disease, the activity of the DNA repair complex was greatly reduced." (PMID 30994454, 2019). "It has been shown that mutated Huntingtin represses PGC-1α, affecting mitochondrial function, hence ribosomal biogenesis may be affected in Huntington’s disease." (PMID 31283791, 2019). "Our data show that Hsp90 is necessary to maintain the levels of REST and mHtt, which suggests that the interactions between Hsp90-REST and Hsp90-Huntingtin could be potential therapeutic targets in Huntington's disease." (PMID 31361762, 2019). "The characterization of the Huntington disease cell model, and the effect of the mutant protein of huntingtin (mHtt), was carried out in the SKSH5Y cell line, inducing its differentiation with retinoic acid, and transfection of the construct, which contains the expansion of the repeated CGT." (PMID 31361762, 2019). "Furthermore, verapamil rescued mutant huntingtin toxicity in Drosophila and zebrafish models of Huntington’s disease, where it also reduced huntingtin aggregate numbers." (PMID 31000720, 2019). "In addition, in mice engineered to produce the mutant version of huntingtin, the accumulation of DNA damage was particularly important in two brain regions that are severely damaged in patients with Huntington’s disease." (PMID 30994454, 2019). "Huntington’s disease (HD) is a progressive neurodegenerative disease caused by an expansion and instability of the cytosine-adenine-guanine triplet repeat (CAG repeat) in the Huntingtin gene." (PMID 28579146, 2019). "Even though as little as 4% recovery of dystrophin expression restores significant muscle function to treat DMD24,25, a higher modification rate is needed in other cases, such as Huntington disease, which requires a 40% reduction of mutant Huntingtin for clinical improvement." (PMID 31636954, 2019). "Our data show that Hsp90 is necessary to maintain adequate levels of REST and mHtt, which suggests that the interaction between Hsp90-REST and Hsp90-Huntingtin could be a potential therapeutic target for treating Huntington's disease." (PMID 31361762, 2019). "Mutant huntingtin (mHtt) undergoes cleavage to release an N-terminal fragment containing the polyglutamine region, and this fragment forms inclusions in individuals affected by Huntington’s disease." (PMID 31527136, 2019). "That Rab5 is taking part of early autophagosome biogenesis is also consistent with previous analysis that used cell culture model of Huntington disease to study the relevance of Rab5-Vps34-Beclin1 complexes in the autophagy-mediated clearance of toxic huntingtin." (PMID 30735514, 2019). "Moreover, several neurodegenerative disorders are associated with the pathological self-assembly of neuronal IDPs, including tau [Alzheimer’s disease (AD)], α-synuclein [Parkinson’s disease (PD)], and huntingtin exon 1 [Huntington’s disease (HD)]." (PMID 31998071, 2019). "Huntingtin is the protein product of HTT, a gene which is mutated in Huntington’s disease (HD) when a normal CAG repeat is expanded to >37 and has been implicated in diverse cellular functions including vesicle trafficking and signaling functions at membranes (reviews)." (PMID 30768638, 2019). "Huntington’s disease (HD), a neurodegeneration characterized by motor, cognitive and psychiatric symptoms is caused by an unstable expansion (CAG) in a polyglutamine (polyQ) tract in the N-terminal of the huntingtin (HTT) gene." (PMID 31450785, 2019).
Huntington disease (continued). "Huntington’s disease (HD) is an adult-onset, inherited autosomal dominant neurodegenerative disorder caused by a polyglutamine (CAG) repeat expansion in exon 1 that encodes the amino-terminal of the huntingtin protein." (PMID 30961637, 2019). "Huntington disease (HD) is a fatal neurodegenerative disorder without a cure that is caused by an aberrant expansion of CAG repeats in exon 1 of the huntingtin (HTT) gene." (PMID 31822756, 2019). "Huntington’s disease (HD) is a monogenic neurodegenerative disorder caused by an expansion of the CAG trinucleotide repeat domain in the huntingtin (HTT) gene, leading to an expanded poly-glutamine (polyQ) stretch in the HTT protein." (PMID 30913220, 2019). "Huntington’s disease (HD) is a dominantly inherited neurodegenerative disorder with motor, cognitive, and psychiatric features caused by expanded HTT CAG trinucleotide repeats that extend a polyglutamine tract in the amino terminus of huntingtin." (PMID 29858077, 2018). "Using cellular and animal models of Huntington disease, we show here that the cytotoxic mutant huntingtin induces neuronal glycogen synthesis and that the increased glycogen protects neurons by suppressing the aggregation of mutant huntingtin." (PMID 29422655, 2018). "Huntington’s disease (Huntington’s chorea, HD) is a severe autosomal dominant disease caused by an increase in the number of CAG (cytosine-adenine-guanine) trinucleotide repeats in the first exon of the huntingtin (HTT) gene." (PMID 30332437, 2018). "Huntington disease (HD) is a fatal dominantly inherited neurodegenerative disorder, caused by expansion of cytosine-adenine-guanine (CAG) repeats in exon 1 of the huntingtin (HTT) gene, resulting in elongated polyglutamine tract in HTT protein." (PMID 30713489, 2018). "In contrast, in a transgenic mouse model overexpressing a truncated N-terminal Huntingtin protein, deletion of the Sirt1 catalytic site worsened Huntington’s disease symptoms while the overexpression of Sirt1 reduced protein aggregation improving physiological conditions." (PMID 30304806, 2018). "Huntington's disease (HD) is an autosomal dominant neurodegenerative disorder causing progressive cognitive and behavioural symptoms as a result of an expansion of CAG repeats within the huntingtin (Htt) gene (Reiner, Dragatsis & Dietrich, 2011)." (PMID 29068134, 2018). "Additionally, loss of IL-1β signaling exacerbated motor deficits and increased the levels of mutant huntingtin in the striatum of the N171-82Q Huntington’s disease (HD) mouse." (PMID 30044427, 2018). "Similarly, a 40% reduction of mutant Huntingtin is sufficient for clinical improvement in models of Huntington’s disease." (PMID 30107853, 2018). "Huntington disease (HD) is an autosomal dominant neurodegenerative disorder manifesting as progressive impairment of motor function and different neuropsychiatric symptoms caused by an expansion of CAG repeats in huntingtin gene (HTT)." (PMID 30120672, 2018). "Huntington’s disease (HD) is an autosomal dominant neurodegenerative disorder that is caused by the expansion of a CAG trinucleotide repeat in exon 1 of the huntingtin (HTT) gene, which is translated into polyglutamine residues (polyQ) in the HTT protein." (PMID 30455632, 2018). "In fact, it has recently been reported that in a mouse model of Huntington’s Disease, exosomes loaded with modified small interfering RNAs (hsiRNAs) targeting Huntingtin mRNA were internalized by primary cortical neurons and were able to induce mRNA and protein silencing." (PMID 28841158, 2017). "Thus though quantification of mutant and wild-type Huntingtin and their cleaved or truncated species in living Huntington’s disease (HD) patients is challenging, it remains a desirable objective." (PMID 29272284, 2017).
Huntington disease (continued). "Likewise, it has been described that exosomes from ADSC has a therapeutic potential for treating Huntington’s Disease decreasing aggregation of mutant Huntingtin, ameliorating abnormal apoptotic protein level and reducing mitochondrial dysfunction." (PMID 28841158, 2017). "Thiazole-containing derivatives of 5-nitro-8-R-quinoline (e.g., MIND4) protect ex vivo rat brain slices transiently transfected with mutant huntingtin and a drosophila model of Huntington’s disease, and activate Nrf2 in a mechanism involving Keap1 Cys-151 modification." (PMID 28820437, 2017). "Furthermore, evidence is mounting that other neurodegenerative disease-associated proteins, such as TDP-43 in ALS/frontotemporal dementia and huntingtin in Huntington’s disease, can also exhibit strain-like behaviour." (PMID 32309596, 2017). "Huntington’s disease is a devastating neurodegenerative disease caused by a CAG repeat expansion in exon 1 of the HTT gene, encoding an expanded polyglutamine in the ubiquitously-expressed HTT protein." (PMID 29272284, 2017). "Huntington disease (HD) is an autosomal dominant neurodegenerative disease that primarily affects the striatum and is caused by a CAG repeat expansion in the first exon of the HTT gene." (PMID 28570578, 2017). "Huntington disease (HD) is a hereditary, relentlessly progressive neurodegenerative disorder caused by a CAG triplet repeat expansion of the HTT gene encoding the protein huntingtin." (PMID 29258585, 2017). "Interestingly, Y-27632 was shown to improve degradation of mutant huntingtin as well as motor performance in the R6/2 mouse model of Huntington’s disease." (PMID 27101974, 2016). "Huntington’s disease (HD) is an incurable hereditary neurodegenerative disorder, which manifests itself as a loss of GABAergic medium spiny (GABA MS) neurons in the striatum and caused by an expansion of the CAG repeat in exon 1 of the huntingtin gene." (PMID 27080129, 2016). "If we could achieve in humans, using a targeted drug molecule, what was seen in Yamamoto’s conditional HTT knockout mouse, we would theoretically treat every facet of Huntington’s disease." (PMID 27421790, 2016). "Researchers have proposed several mechanisms to explain how aggregates of one such mutant protein, called mutant Huntingtin (mHtt), might contribute to Huntington's disease." (PMID 27484239, 2016). "Likewise, the longer the polyQ tracts in the huntingtin gene, the sooner the onset of Huntington's chorea." (PMID 27508340, 2016). "Accruing evidence suggests that prion-like behavior of fibrillar forms of α-synuclein, β-amyloid peptide and mutant huntingtin are responsible for the spread of the lesions that characterize Parkinson disease, Alzheimer disease and Huntington disease, respectively." (PMID 26820848, 2016). "Likewise, TDP-43, a cardinal protein in FTD and ALS, and huntingtin, a protein responsible for Huntington’s disease, were elevated in the urea-soluble fraction of the extracts from the Hrsflox/flox; CaMKIIα-cre mice." (PMID 27112194, 2016). "Insoluble aggregates can be formed as a result of covalent cross-links among peptide chains, as in the case of amyloid-β-peptide (Aβ) in Alzheimer disease (AD), α-synuclein in Parkinson disease (PD), huntingtin in Huntington disease (HD), and SOD1 in amyotrophic lateral sclerosis (ALS)." (PMID 26881020, 2016). "Huntington’s disease (HD) is an autosomal dominant neurodegenerative disorder of the central nervous system (CNS) that is defined by a CAG expansion in exon 1 of the huntingtin gene leading to the production of mutant huntingtin (mHtt)." (PMID 27221146, 2016). "Huntington’s disease (HD) is a progressive neurodegenerative genetic disease associated with a wide variety of motor impairment and psychiatric symptoms caused by excessive CAG trinucleotide expansions of Huntingtin gene (HTT)." (PMID 25354658, 2015).
Huntington disease (continued). "The mutation is thought to introduce a gain-of-toxic function in the mutant huntingtin protein, and blocking this toxicity by antibody binding could alleviate Huntington disease pathology." (PMID 25294428, 2015). "EVs have been suggested as potential carriers in the intercellular delivery of misfolded proteins associated to neurodegenerative disorders, such as tau and Aβ in AD, α-synuclein in Parkinson’s disease (PD), SOD1 in amyotrophic lateral sclerosis (ALS) and huntingtin in Huntington’s disease (HD)." (PMID 25741766, 2015). "QBP1-HSC70bm peptides, which contain two mutant Huntingtin protein binding domain-polyglutamine binding peptide 1 (QBP1) domains and two HSC70 binding motifs (HSC70bm) reduced mutant Huntingtin protein aggregates and ameliorated the Huntington disease phenotype in a mouse model." (PMID 26415220, 2015). "Huntington disease, a neurodegenerative disease characterized by progressive motor dysfunction and dementia, is caused by a larger than 35 CAG trinucleotide repeat expansion, which results in a long mutant polyglutamine tract in the huntingtin (HTT) protein." (PMID 25699594, 2015). "Huntington disease, unlike AD and PD, is an autosomal disorder caused by trinucleotide expansion within the huntingtin gene." (PMID 25774133, 2015). "Huntington's disease (HD) is a currently incurable, autosomal dominant neurodegenerative disease resulting from the expansion of the trinucleotide (CAG) repeat region of the huntingtin (HTT) IT15 gene, encoding huntingtin protein (Htt)." (PMID 25257175, 2015). "This hypothesis is consistent with the alterations of the nuclear envelope in cells containing inclusion bodies that were described in patients affected by Huntington disease and in transgenic mice expressing mutant huntingtin." (PMID 25191266, 2014). "Huntington's disease (HD) is characterized by a number of certainties: It is inherited, fully penetrant, neurodegenerative, progressive, fatal, and caused by CAG repeat expansions in the gene encoding huntingtin." (PMID 25155142, 2014). "The autosomal dominant inheritance pattern of Huntington’s disease suggests the importance of the mutant protein, huntingtin, in pathogenesis of Huntington’s disease, but wild type huntingtin also has been shown to be important for neuronal functions such as axonal transport." (PMID 25054562, 2014). "With regard to Huntington's Disease, normal huntingtin is associated with NMDARs via PSD-95 but mutant huntingtin impairs the interaction between PSD-95 and huntingtin, leading to excitotoxicity through increased NMDA receptor activity, which is a key feature of this neurodegenerative disease." (PMID 26317010, 2014). "As a broad range of N-terminal fragments of expanded huntingtin is present in the brain of patients with Huntington disease, fragments may aggregate into different kinds of oligomers and, thus, generate a heterogeneous population of oligomers." (PMID 24961702, 2014). "One protein that may regulate the switch from actin- to microtubule-based movement of endocytic compartments is Huntingtin (Htt), in which expansion of poly-glutamine repeats leads to Huntington's disease." (PMID 24727350, 2014). "Huntington’s disease (HD) is an autosomal dominant, progressive, fatal, neurodegenerative disorder caused by an expanded CAG tract (polyglutamine or PolyQ) in exon one of the huntingtin gene." (PMID 25140802, 2014). "Huntington’s disease (HD, OMIM # 143100) is an autosomal dominant neurodegenerative disorder caused by an expansion of a polymorphic CAG trinucleotide repeat in the first exon of huntingtin (HTT), the gene encoding huntingtin protein." (PMID 24751919, 2014). "However, the results also include more descriptive terms such as Huntington’s Disease, huntingtin, Transferases, drug interaction, and solute carrier family 6 (neurotransmitter transporter, serotonin)." (PMID 23409969, 2013).